TLR2 (toll like receptor 2)
Diseases named in the same sentence as TLR2 in open-access papers (continued):
Sharing a sentence is not in itself a finding about the gene and the disease.
infection (continued). "Analysis of blood transcriptional modules demonstrated that monocytes and B-cells were the predominantly activated cell types in animals that showed resolution of infection, which was similar to the response of TLR2-stimulated PBMCs." (PMID 33414473, 2021). "Recently published experiments showed a recognition of infection with C. diphtheriae by TLR2 and TLR9." (PMID 33805570, 2021). "The lard diet group presented with an increased parasitic load in the heart and adipose tissues following infection as well as an increased expression of Tlr2 and Tlr9 in the heart." (PMID 34113663, 2021). "Several TLRs have been described as important molecules in the resistance to T. cruzi experimental infection, such as TLR2, TLR4, TLR7, and TLR9." (PMID 34336720, 2021). "Infection by SARS-CoV-2 induces the release of a proinflammatory cytokine such as IL-1β through activation of TLR2 (toll-like receptor 2), TLR3, or TLR4." (PMID 34306796, 2021). "Our previous work has shown that monocytes from CL patients express ex vivo and after infection with L.braziliensis more TLR2 and TLR4 than monocytes obtained from healthy individuals; again, this was linked to TNF expression." (PMID 34691019, 2021). "In our study, TLR2 approached significance when comparing CT positive women with a symptomatic course of infection to CT positive women with an asymptomatic course of infection." (PMID 33430411, 2021). "The importance of macrophage TLR2 for phagocytosis and ROS production during infection with L.m has been demonstrated previously." (PMID 34194428, 2021). "TLR2 has been shown to play an important role as a mediator in the innate immune response to a CT infection." (PMID 33430411, 2021). "The stealth properties of HBV have recently been questioned, and it has been shown that in the early phase of infection primary human hepatocytes (PHH) sense HBV particles via toll-like receptor 2 (TLR2)." (PMID 32632817, 2021). "After 48 hours of infection, a decreased frequency of infected cells was observed following the neutralization of TLR2, 54% (31-62%), and TLR4, 45% (39-62%), versus 84% (72-91%) in non-neutralized monocytes (p<0.05)." (PMID 34691019, 2021). "These resistant animals begin to express TLR2 from 6 h post-infection reaching a peak at 24 h, while hamsters show late expression." (PMID 35046936, 2021). "Our work suggests that the canonical Mtb virulence factors PDIM and ESX-1 function to blunt a distinct, endosome-specific component of the TLR2 response, and that this interference in fact modulates infection outcomes in macrophages and in mice." (PMID 34755600, 2021). "In this study, the transcriptional profiling of specimens from animals infected with woodchuck hepatitis virus (WHV) indicated TLR2 mRNA accumulation as most strongly impacted during WHV infection resolution as compared to other mRNAs." (PMID 33414473, 2021). "TLR2 expression was significantly lower in PMN in the BAL after liver crush compared with laparotomy-only plus infection." (PMID 34520397, 2021). "Having observed that TLR2 is involved in the inhibition of autophagy in N. caninum infection, we decided to verify the anti-infection role of TLR2." (PMID 34900761, 2021). "Interleukin 6 cytokine is one of the major cytokines which are released during interaction of LPG (Lipophosphoglycan) with TLR2 at an early stage of infection." (PMID 35011356, 2021). "As the full extent of the immune response likely involved independent as well as synergistic effects, we employed both TLR4 and TLR2 to stimulate immune cells from the blood and to artificially recreate a multiorganism infection." (PMID 34439987, 2021). "Infection with wild-type Mtb induced a similar degree of cell death in wild-type and Tlr2-/- macrophages." (PMID 34755600, 2021). "Although a fundamental feature of TLR2 signaling, the two transcriptional response components are likely to have different relevance in the context of individual infections." (PMID 34755600, 2021).
infection (continued). "In mid-later stages of infection, however, the attenuated type I IFN signal by the NOD2 deficiency would be sufficiently compensated by the operation of other PRRs such as TLR2 and TLR4." (PMID 34777348, 2021). "Our results were in accordance with previous studies, suggesting that TLR2 contributed to the proliferation and resistance to infection in N. caninum." (PMID 34900761, 2021). "Same probiotic supplementation increased the TLR2 regulation in cecal tonsils of S. enteritidis-infected chickens that helped in lowering the infection level." (PMID 34512716, 2021). "For example, the mycelium of C. albicans binds to tool-like receptor 2 (TLR2) on monocytes, thereby increasing the level of the anti-inflammatory cytokine IL-10 during infection." (PMID 33680221, 2021). "Some found that, during infection of murine macrophages, TLR2, TLR5, and TLR9 are required for an optimal cytokine response." (PMID 34280250, 2021). "Phthiocerol dimycocerosate (PDIM) and ESX modulate TLR2-dependent infection outcomes in macrophages and mice." (PMID 34755600, 2021). "In support of this, it was shown that O. tsutsugamushi-infected Toll-like receptor 2 (TLR2)-/- C57BL/6 mice were even better protected from lethal infection compared to wild-type mice and showed lower bacterial burden and milder symptoms of disease." (PMID 34452021, 2021). "Similar to findings for MYD88, expression of representative genes upon infection with wild-type Mtb or PDIM or ESX-1 mutants was entirely lost in Tlr2-/- BMDM." (PMID 34755600, 2021). "CYP3A4 rs2242480C>T, SLC22A11 (OAT4) rs11231809T>A, TLR2 rs4696480T>A, and IL6 rs1800796C>G genetic polymorphisms are associated with the incidence of infections among patients undergoing cytotoxic chemotherapy." (PMID 33776761, 2021). "Further, TLR2 contributed to the attenuated phenotype of one of these mutants in a murine model of infection." (PMID 34755600, 2021). "The expression of TLR2 mRNA was significantly increased on the 24th and 40th days after infection, and the expression of TLR9 mRNA on the 31st and 40th days after infection also showed an up-regulated trend." (PMID 34988138, 2021). "Previous studies have demonstrated that TLR2 signaling is essential to protect the host against infection by N. caninum." (PMID 34900761, 2021). "Previously, it has been shown that the infection of murine bone marrow derived neutrophils with Leishmania infantum induced iNOS mRNA expression and NO production in a TLR2-dependent manner." (PMID 33747981, 2021). "The relationship between TLR2 and caspase-1 is also supported by the disparate kinetics of each KO mouse during infection." (PMID 32290861, 2020). "The increased tissue pathology of TLR2 KO versus caspase-1 KO animals agrees with the finding that S. aureus burden was increased early post-infection and more dramatically in TLR2 KO mice." (PMID 32290861, 2020). "TLRs (especially TLR2, 4 and 5) in the CF lung are one of the most common innate immune defences activated in response to infection leading to the activation of the classical NF-kB-activation and subsequent pro-inflammatory cytokine release." (PMID 33031374, 2020). "To assess the role of TLR2 in C. t.‐elicited inflammation, we treated HEKs cells with nonspecific targeting (control) Ctrl‐ or TLR2‐siRNA for 48 hours before C. t.‐infection." (PMID 31912662, 2020). "The TLR2 expression in the kidneys of the immunocompetent Acanthamoeba spp.-infected mice remained at a similar level during the infection." (PMID 32958053, 2020). "After infection, increased amounts of EVs are released from infected macrophages that interact with TLR2 and stimulate the translocation of NF-κB." (PMID 32266161, 2020). "Toll‐like receptor 2 (TLR2) is a pattern recognition receptor that is critical in mediating immune responses ranging from tolerance induction to controlling infection by multiple pathogens and mediating tumor regression." (PMID 32696994, 2020).
infection (continued). "Compared with non-infected mice, mice submitted to S. pneumoniae stimulation expressed higher levels of Tlr2 and Myd88 mRNA at 24 h after infection in both the cortex and the hippocampus." (PMID 32676082, 2020). "Following infection, the level of TLR2 mRNA in the lungs of klotho WT mice was stable but was significantly increased in KO mice at 1 and 3 days post-infection." (PMID 33329595, 2020). "By contrast with these findings, in this study, we found that the infection of novirhabdoviruses increased the expression of TLR2 in flounder cells." (PMID 32986779, 2020). "TLR2/4 plays positive roles in the induction of immune responses against Mtb and participates in eradication of the infection, while IL-10 can have deleterious effects on the patients during active TB disease in terms of bacterial clearance." (PMID 33202583, 2020). "This study aimed to investigate the association between TLR2 and TLR4 polymorphism and the risk of acquiring severe infections, and impact on AML patient’s outcome." (PMID 33247673, 2020). "We verified that P. brasiliensis increased α3 integrin levels in A549 cells after 5 h of infection and promoted interaction between this receptor and TLR2." (PMID 33173103, 2020). "Taken together, these results demonstrated that infection with S. uberis changed the redox status in mammary glands as well as in MECs, and TLR2 played an essential role in this process, especially in MECs." (PMID 32098158, 2020). "Infection of WT mice with Δhly resulted in significant levels of IL-10, but unlike in BMMs Δhly also induced significant amounts of IL-10 in TLR2-/- mice, suggesting that bacterial lipoproteins were not the dominant IL-10-inducing molecules in mice." (PMID 32634175, 2020). "In other terms, tolerance through TLR2 interaction is mostly favored in a setting of chronic well-tolerated infection." (PMID 31992837, 2020). "At the beginning of infection in immunocompetent mice, TLR2 expression was observed in most cardiomyocytes." (PMID 32958053, 2020). "Recently they also discovered that in TLR2−/−TLR4−/− mice infected with polymicrobial infection including P. gingivalis, T. denticola, T. forsythia, and F. nucleatum, atherosclerotic plaque progression was significantly reduced." (PMID 32002588, 2020). "This led us to study a possible interaction between nicotine and TLR2/TLR4 in macrophages during infection." (PMID 33212859, 2020). "Secretion of IL-10 in response to infection with the parental strain was mostly TLR2-dependent, while IL-10 secretion in response to lysozyme-sensitive strains was dependent on TLR2 and Unc93b1." (PMID 32634175, 2020). "In this work, we show that, after 24 h post-infection with P. brasiliensis, A549 lung epithelial cells presented higher TLR2 levels, which is important for IL-8 secretion." (PMID 33173103, 2020). "In the current study, we demonstrate that the MyD88-dependent receptor TLR2 is critical for S. aureus containment in the brain and galea during craniotomy infection." (PMID 32290861, 2020). "The levels of MDA and UCP2 were significantly increased due to the infection of S. uberis in WT, TLR2−/−, and TLR4−/− mice (p < 0.05)." (PMID 32098158, 2020). "The TLR4 expression in the immunocompetent Acanthamoeba spp.-infected mice was similar to TLR2 expression and remained at a similar level during the infection." (PMID 32958053, 2020). "Since yeasts only rarely cause an infection in humans, we examined also the effect of lipoteichoic acid (LTA), a TLR2 agonist that is a major constituent of the bacterial wall in common gram-positive pathogens." (PMID 32059733, 2020). "We demonstrate that phagocytosis and reactive oxygen species during infection with conidia are TLR-2– and TLR-4–dependent and are essential for conidial killing." (PMID 33193308, 2020).
infection (continued). "Tlr2 expression increased in some organs of channel catfish (Ictalurus punctatus) and orange-spotted grouper (Epinephelus coioides) during infection with the ciliate ectoparasites I. multifiliis and C. irritans respectively." (PMID 33076342, 2020). "The level of TLR2 mRNA was significantly lower in the lungs of klotho KO mice than in those of klotho WT mice at 3 days post-infection." (PMID 33329595, 2020). "An interesting finding was that some mediators were more affected by TLR2 loss in the brain compared to the galea, including IL-1β, CCL2, TNF-α, IL-6, and CXCL2, which was particularly evident at day 14 post-infection." (PMID 32290861, 2020). "After infection, the expression of TLR2 protein was detected by Western blot, and cell proliferation and the cell cycle were detected by the CCK-8 method and fluorescence-activated cell sorting." (PMID 32256204, 2020). "Collectively, these findings demonstrate that the host mounts an initial immune response to S. aureus craniotomy infection that is TLR2- and caspase-1-dependent, with IL-1β being a key player." (PMID 32290861, 2020). "In the current study, following infection of rohu with A. invadans, TLR2, TLR3, TLR4 and TLR9 were downregulated." (PMID 33177569, 2020). "In this study we also blocked TLR4 with TLR4-IN-C34 antagonist which did not affect the inflammatory response in MAP-infected macrophages, which confirms that MAP interaction with TLR2 is key during infection." (PMID 33212859, 2020). "In contrast, bacterial burden was most affected in caspase-1 KO mice at day 14 post-infection, in agreement with caspase-1 activity occurring subsequent to TLR2 signaling to maximize IL-1β production." (PMID 32290861, 2020). "Although protective roles of TLR2 signaling have been suggested in models of intravenous infection, localized responses to infections have displayed variable outcomes." (PMID 33256638, 2020). "In summary, this work shows that during early infection (5 h), P. brasiliensis yeasts induce a raise in α3 integrin levels in A549 epithelial cells, while TLR2 levels are similar to those of uninfected cells." (PMID 33173103, 2020). "These animals also had higher fungal loads during infection with F. pedrosoi conidia, confirming that TLR-2 and TLR-4 are essential receptors for F. pedrosoi recognition and immune system activation." (PMID 33193308, 2020). "Similar to our findings with TLR2 KO animals, caspase-1 also contributed to S. aureus containment during craniotomy infection but with distinct kinetics." (PMID 32290861, 2020). "Specifically, heightened bacterial burdens were primarily evident at day 14 post-infection in the galea and brain of caspase-1 KO animals, whereas TLR2 was critical during acute infection (i.e., day 3) and beyond." (PMID 32290861, 2020). "Herein; we investigated the impact of the TLR2 and TLR4 polymorphisms on the susceptibility of AML patients to infection as well as patient’s outcome." (PMID 33247673, 2020). "Bacterial counts remained elevated at day 14 post-infection, whereupon a significant number of bone flaps were extruded by day 21 in TLR2 KO mice (~ 40%), which was attributed to erosion of the overlying skin resulting from unchecked bacterial replication." (PMID 32290861, 2020). "By contrast, deletion of the hylB gene in GBS resulted in amplified lethality that was eliminated in infection studies conducted in Tlr2 gene knockout mice." (PMID 33072013, 2020). "Activated macrophages were preincubated with 0, 2.5, 5, 10 or 20 μg/mL of either MMG11 (TLR2 antagonist) or T6167923 (MyD88 inhibitor), followed by infection with MAP for 24 h." (PMID 33212859, 2020). "Our findings identified a critical role for both TLR2 and caspase-1 in preventing bacterial outgrowth in the brain, galea, and bone flap during S. aureus craniotomy infection, suggestive of pathway cooperativity." (PMID 32290861, 2020).
infection (continued). "In the present study, ETEC K88 appeared to be a causing factor for the significant increase of TLR2 mRNA expression and the pretreatment of L. salivarius in ETEC K88-infected groups further elevated the mRNA expression of TLR2 within 3–12 h infection." (PMID 32774852, 2020). "In the present study, we found upregulation of both TLRs in immunocompromised Acanthamoeba spp.-infected mice, but statistically significant differences were only found in TLR2 expression on the decline of infection." (PMID 32958053, 2020). "Since TLRs play an important role in eliciting proinflammatory cytokines during infection with A. baumannii, we analyzed the expression levels of TLR2, 4, and 9 in the lungs of klotho WT and KO mice after infection with A. baumannii." (PMID 33329595, 2020). "In unpretreated MSC group, a comparable level of IFN-γ and IL-5 compared to infection control was observed, and in the TLR2+IFN-γ-treated MSC group, only a medium increase of the level of IFN-γ and comparable IL-5 level to the infection control were visible." (PMID 32503644, 2020). "Previous study showed that TLR3 and TLR5 were upregulated at 24, 48 and 72 h post-infection in A549 pulmonary epithelial cells treated with Mtb, and the expression of neutrophil TLR2 is also increased in PTB patients." (PMID 32811479, 2020). "In the present study, a significant upregulation of TLR2 expression was seen in the heart of immunocompetent mice at the beginning of infection." (PMID 32958053, 2020). "To further analyze these RNAseq data, we chose the genes with a threshold of a P-value less than 0.05 in tlr2+/− with Mm infection (1102 up- and 827 down-regulated genes)." (PMID 31747871, 2019). "TLR2 has been shown to be important for granuloma formation in Mtb infection in mouse infection model." (PMID 31747871, 2019). "We also demonstrate that following in vitro infection with L. braziliensis, TLR2 and TLR4 expression is up-regulated in cells from CL patient monocytes as compared to HS monocytes." (PMID 31119102, 2019). "Most important for the purpose of this study was our demonstration that within each infection experiment, the TLR2 genotypes were exposed to the same infectious tick bite challenge." (PMID 31040326, 2019). "The same study also demonstrated that MyD88-deficient mice have a more dramatic increase in bacterial burden than Tlr2 knockouts after intratracheal infection with virulent C. burnetii Nine Mile phase I." (PMID 30800124, 2019). "The infection induced expression of this chemokine is dependent on Myd88, the common adaptor of the majority of Tlrs, including tlr2." (PMID 31747871, 2019). "Consistent with in vitro effects, BCG85C5 markedly expanded both effector and central memory T cells in C57Bl/6 mice protecting them against both primary aerosol infection with Mtb and reinfection, but was less effective among TLR-2 knockout mice." (PMID 31396406, 2019). "Infection with S. Typhimurium and S. Dublin led to a significant downregulation of TLR2, TLR3, TLR4, TLR5, and TLR7 in chicken macrophages HD11, whereas only a slight downregulation of TLR3 and TLR7 genes was observed in the S. Gallinarum infection group." (PMID 31998655, 2019). "MNV-infected macrophages that were primed with the TLR2 agonist Pam3CSK4 secreted IL-1β into the culture supernatant starting 12–16 hours post-infection." (PMID 31017981, 2019). "It is unclear how TLR2-mediated recognition of fibrillar PfMSP2 impacts infection-induced immune responses elicited by native, parasite-associated PfMSP2 in vivo, but it is of interest and will require further study." (PMID 31227760, 2019). "To prove that the TLR2-mediated signalling pathway is used by Mtb to disrupt macrophages' functional response, we blocked the activity of the TLR2-related signalling proteins in macrophages before infection." (PMID 31871425, 2019).